LOXL2 (lysyl oxidase like 2)
Diseases named in the same sentence as LOXL2 in open-access papers (continued):
Sharing a sentence is not in itself a finding about the gene and the disease.
tumor (continued). "Nowadays, numerous studies have firmly established the implication of LOXL2 in the progression and metastasis of various tumour types." (PMID 37762708, 2023). "EA was found to decrease tumor collagen deposition through lysyl oxidase-like protein-2 (LOXL2) suppression." (PMID 38002335, 2023). "Collectively, these findings suggest that LOXL2 is a potent regulator of integrin α5β1 protein levels and has a pro-tumor effect in ccRCC." (PMID 37483505, 2023). "The utility of this model is demonstrated with the inducible knockdown of LOXL2 inhibiting primary tumor growth as well as PNI." (PMID 37746297, 2023). "A positive feedback loop between stiffness-induced zinc finger E-box binding homeobox 1 (ZEB1) expression and ZEB1/LOXL2-induced ECM stiffness remains tumor cells in a mesenchymal state." (PMID 36906534, 2023). "Combined with our finding that DHA affects VEGFA expression by directly regulating the LOXL2, it was reasonable to presume a synergistic anti-tumor effect of DHA combined with VEGFR-TKIs." (PMID 37056396, 2023). "The secreted LOXL2 regulates integrin levels to promote tumor progression in renal clear cell carcinoma (ccRCC) by regulating lysyl oxidase LOXL2 status and its correlation with tumor staging." (PMID 37483505, 2023). "In 2003, LOXL2 was first identified as a promoter of tumour progression and, over the course of two decades, numerous studies have firmly established its involvement in multiple cancers." (PMID 37762708, 2023). "Taken together, these data suggest the presence of a functional interaction between BRD4 and LOXL2, which may underlie future therapeutic interventions for cancer treatment, and which we therefore further investigated at the molecular, cellular, and tumor levels." (PMID 37937685, 2023). "The expression of LOXL2 in tumor tissues and cancer cell lines has been found to be both down–regulated and up–regulated, suggesting differing roles in cancer." (PMID 37886979, 2023). "It was confirmed that Mia GR tumorigenicity was higher than Mia Con and that LOXL2 knockdown had an inhibitory effect on tumor volume." (PMID 37737908, 2023). "It was found that LOXL2 is highly expressed in tumor cells and promotes tumor cell invasion and metastasis." (PMID 37351348, 2023). "In contrast, Loxl2 overexpression promoted primary and metastatic tumour growth and decreased overall survival." (PMID 37762708, 2023). "Intracellular LOXL2 also influences cytoskeleton dynamics and cell motility capabilities to promote tumour migration and metastasis." (PMID 37762708, 2023). "Our model’s utility was demonstrated with inducible ablation of LOXL2 reducing primary tumor growth and PNI." (PMID 37746297, 2023). "We performed a review of the current knowledge on the roles LOXL2 performs in the modulation of the HCC tumor microenvironment, formation of premetastatic niches, and epithelial-mesenchymal transition." (PMID 37511503, 2023). "Tumour-secreted LOXL2 can also contribute to the early steps of metastatic colonisation at distant organs." (PMID 37762708, 2023). "Recent studies have also implicated LOXL2 in the regulation of epithelial-to-mesenchymal transition (EMT) and tumor progression." (PMID 37746297, 2023). "In both cases, tumour-secreted LOXL2 activates surrounding fibroblasts to create a supportive local niche." (PMID 37762708, 2023). "Where there was tumor growth, ablation of LOXL2 resulted in 16% PNI development (1/6 mice) in contrast to uninduced control tumors showing 50% PNI (5/10 mice)." (PMID 37746297, 2023). "EVs released from tumor cells during hypoxia participate in the EndMT switch of TECs, particularly EVs loaded with lysyl oxidase-like 2 protein (LOXL2)." (PMID 37108672, 2023). "Extracellular LOXL2 exerts its effects on tumour cells and the tumour microenvironment at different levels." (PMID 37762708, 2023).
tumor (continued). "Inducible ablation of LOXL2 expression using lentiviral delivered shRNA reduced incidence of primary tumor growth in the mouse model (LOXL2 ablation with doxycycline addition - 40% (6/15 mice) versus vehicle only - 66% (10/15 mice)." (PMID 37746297, 2023). "Despite the accumulated evidence for LOXL2’s intracellular functions, the mechanisms of LOXL2’s actions promoting tumor progression are not yet fully understood." (PMID 37298909, 2023). "LOXL2 has been associated with different processes in cancer progression, for example, EMT, tumor cell invasion, tumor progression, and regulation of epidermal differentiation." (PMID 36483731, 2022). "Here, our in vitro and in vivo results showed that L2Δ13 facilitates glycolysis and tumor cell proliferation more efficiently than full-length LOXL2 in tumor progression." (PMID 36209516, 2022). "We have previously demonstrated that cytoplasmically localized LOXL2, as well as L2Δ13, induces cytoskeletal reorganization to promote tumor invasion and metastasis." (PMID 36209516, 2022). "Specifically, the increased expression of LOX, LOXL1 and LOXL2 appears to be correlated with similar trends in terms of patient survival, tumour infiltrates and correlation with expression of genes involved in tumour-related processes." (PMID 35800439, 2022). "The development of subcutaneous tumors from implanted KYSE510 cells silenced for LOXL2 expression was strongly inhibited, whereas re-expression of LOXL2 or L2Δ13 in the LOXL2-silenced cells partially restored tumor development." (PMID 36209516, 2022). "Lysyl oxidase-like 2 (LOXL-2), a collagen-modifying enzyme, has been found to increase the stiffness of tumor tissue by modifying the ECM components in the TME in HCC, thereby promoting intrahepatic metastasis." (PMID 36120364, 2022). "Overwhelming evidence has accumulated suggesting that the expression of several lysyl oxidases, in particular LOX and LOXL2, is enhanced in the hypoxic tumor microenvironment." (PMID 35682926, 2022). "Several of these genes, in particular lysyl oxidase (LOX) and lysyl oxidase like-2 (LOXL2) were identified as genes that are upregulated by hypoxia, and promote tumor cells invasion and metastasis." (PMID 35682926, 2022). "LOXL2-induced alterations of ECM organization are associated with the induction of abnormal fibrosis, which in tumors promotes tumor cell invasiveness and tumor metastasis." (PMID 36209516, 2022). "LOXL2 promoted tumor progression by remodeling HNSCC extracellular matrix and increasing epithelial-mesenchymal transition (EMT)." (PMID 35775082, 2022). "Impairment of the ECM with an anti-LOXL2 antibody in vivo facilitated tumor progression and lowered the OS outcomes." (PMID 35911730, 2022). "High mRNA levels of LOX and LOXL2 were associated with advanced PDAC stage, while elevated LOX and LOXL3 expression correlated with high tumor grade." (PMID 35433829, 2022). "Among these proteins, LOXL2 is considered to be an important regulator of tumor progression, and previous studies reported that LOXL2 is significantly overexpressed in human HCC tissues compared to nontumor tissues." (PMID 36254230, 2022). "For non-neoplastic diseases, EV contents also exert important regulatory roles as they mediate EC function, with miR-125a, miR-210, miR-375, miR-214, lysyl oxidase like-2 (LOXL2), and HSP70 having significant roles in this process." (PMID 35752798, 2022). "As for the KPC GEMM mice at different time points, the tumor stained strongly at 25 days, 3 months, and 7 months, indicating that Loxl2 was expressed early in the KPC models, thereby establishing it as an excellent marker for early diagnosis of PDAC in mice." (PMID 36002889, 2022). "In tumor tissues, an increased LOXL2 facilitates endothelial invasion, which is a critical step in neo-angiogenesis, most probably through the increased motility of endothelial cells." (PMID 36114508, 2022).
tumor (continued). "Taken together, our results demonstrate that the lysyl-oxidase-independent effects of L2Δ13/LOXL2 contribute to tumor progression via enzyme mobilization and enhanced glycolysis." (PMID 36209516, 2022). "LOXL2 depletion strikingly inhibited the tumor cell proliferation of the TE1 and KYSE510 cells, as determined by the measurement of DNA synthesis and cell colony formation." (PMID 36209516, 2022). "Recently, there has been a new understanding of the pro-metastatic mechanism of LOXL2: circulating tumor cell (CTC) clusters can strengthen the metastatic ability of tumor cells." (PMID 36293126, 2022). "Lysyl-oxidases such as LOX and LOXL2 also function as pro-angiogenic factors that also contribute to tumor metastasis." (PMID 36232621, 2022). "It is demonstrated that inhibition of LOXL2 inhibits tumor angiogenesis in several types of solid tumors." (PMID 35682926, 2022). "Numerous clinical studies have also confirmed that high LOXL2 expression is related to tumor grading, poor prognosis, and reduced survival rate." (PMID 36293126, 2022). "Although a few studies have shown the tumor suppressive effects of LOXL2, most of them cannot be verified in clinical samples." (PMID 36293126, 2022). "It is also reported that LOXL2 promotes oncogenic tumor progression in alveolar rhabdomyosarcoma, independently of its catalytic activity, and possibly as a result of its interaction with the intermediate filament protein vimentin." (PMID 35682926, 2022). "Secreted lysyl oxidases, such as LOX and LOXL2, also influence the spread of tumor cells to distant sites by another mechanism." (PMID 35682926, 2022). "Lysyl oxidase–like 2 (LOXL2) has been recognized as an attractive drug target for anti–fibrotic and anti–tumor therapies." (PMID 36362176, 2022). "In LUAD, LOXL2 was demonstrated to contribute to cell surface matrix remodeling and subsequently bring dissemination of tumor cell aggregates." (PMID 36276289, 2022). "Overexpressed LOX was found to promote angiogenesis, and expression level of LOXL2 was higher in HCC than in non-tumor tissue." (PMID 35311155, 2022). "Tumor-derived eCAFs (Cluster 3) are characterized by high expression of genes associated with tumor invasion (MMP14, LOXL2, and POSTN), indicating that eCAFs constitute an essential component of the TME for tumor metastasis." (PMID 34976204, 2022). "OSM can contribute to ECM remodeling by upregulating LOXL2 expression in tumor cells, thereby enhancing the invasive ability of IDC cells." (PMID 36293126, 2022). "Significant upregulation of LOXL2 has been observed in metastatic/invasive phenotypes of tumor cells and tumors as well as fibrotic disorders." (PMID 35682561, 2022). "Noncoding RNAs and hypoxic-derived EXOs are involved in the regulation of tumour progression.High expression of lysyl oxidase like 2 (LOXL2) was previously found in metastatic human HNSCC cells in a mouse model of lymph node metastasis." (PMID 33478586, 2021). "Reduction in tumor collagen deposition through Lysyl oxidase-like 2 (LOXL2) suppression increases T cell infiltration, diminishes exhausted T cells and abrogates resistance to anti-PD-L1." (PMID 34733848, 2021). "The 76GS score showed a negative correlation with LOXL2 and as expected, the other two scores (KS, MLR) showed a positive correlation with LOXL2 across all tumor datasets." (PMID 33807227, 2021). "Compared to xenografts from the control group, LOXL2 knockdown robustly repressed tumor growth, which was further confirmed by IHC staining of the proliferation index PCNA." (PMID 34836938, 2021). "Univariate and multivariate analyses revealed that LOXL2 expression was an independent predictor for the overall survival in addition to tumor size, tumor differentiation, and lymph node metastasis." (PMID 34836938, 2021). "The present study was undertaken to study the association of HIF-1α with LOXL-2 in OSCC and their role in tumor progression." (PMID 33639646, 2021).
tumor (continued). "We showed here that GluR1/2 are acetylated by acetyltransferase CBP upon glutamate stimulation of various tumor cells, and acetylated GluR1/2 can be deacetylated by Loxl2." (PMID 33446662, 2021). "LOX- and LOXL2-mediated tumour progression is due primarily to ECM modifications but relies in part on intracellular signalling." (PMID 33544155, 2021). "Serum sEV LOXL2 can reflect a hypoxic and aggressive tumor type and can serve as an alternative to tissue LOXL2 as an independent prognostic factor of overall survival for patients with HNSCC." (PMID 34646366, 2021). "They identified that the silencing of LOLX2 (lysyl oxidase-like 2), a target gene of Hs_miR-218_3p, inhibited migration and invasion in tumor cells." (PMID 33640023, 2021). "This in turn endowed the cells with stem-like properties leading to their escape from tumor dormancy both in vitro and in vivo, while inhibiting LOXL2 expression prevented their outgrowth." (PMID 33987095, 2021). "LOXL2 secretion induces, at distance to the tumor, collagen crosslinking, ECM stiffness and durotaxis-dependent BMDC recruitment." (PMID 34298680, 2021). "The spatial-temporal heterogeneity of the LOXL2 concentration and thus the mechanical stiffness also has direct implications for migrating cells that attempt to escape the primary tumor." (PMID 33807227, 2021). "Immunoexpression of both HIF-1α and LOXL-2 was analyzed both quantitatively and qualitatively and compared with tumor stage, nodal stage, clinical stage, and histological grade." (PMID 33639646, 2021). "Correspondingly, increased tumor growth and liver metastasis were obtained after LOXL2 overexpression." (PMID 34836938, 2021). "The HIF-1α expression and the LOXL-2 expression were compared with the tumor category, nodal stage, clinical TNM stage, and histological grade using Kruskal–Wallis test." (PMID 33639646, 2021). "In our report, we illustrated that the expression of LOXL2 in GC tissues was higher than that in normal tissues, and this expression was markedly correlated with tumor stage and poor OS in patients with GC, which was consistent with reports above." (PMID 35126449, 2021). "Our research in addition suggests that OSM-induced LOXL2 also promotes metastatic events through the alignment of collagen I fibers found abundantly in the stroma, allowing mesenchymal-like tumor cells to efficiently migrate into vasculature and nearby tissue." (PMID 34011405, 2021). "Loxl2 increases the expression level of vegf in cancer, while angiogenesis contributes to primary and metastatic cancer growth, and it is necessary for tumor progression." (PMID 34943209, 2021). "Previous studies have shown that overexpression of LOX and LOXL2 can increase the abnormal crosslinking of collagen, promote fibrosis remodeling, and accelerate the malignant progression of the tumor." (PMID 34335820, 2021). "LOXL2 can promote the survival and drug resistance of tumor cells, regulate cell adhesion, movement and invasion, and reshape the TME." (PMID 34552612, 2021). "Localization of LOXL-2 staining was compared with the tumor category, nodal stage, clinical TNM stage, histological grade, and areca nut chewing habit using Chi-square test." (PMID 33639646, 2021). "LOXL2 has been considered as a tumor promoter, how precisely it contributes to malignant phenotypes remains incompletely understood." (PMID 34836938, 2021). "LOXL2-enriched sEV-treated mice showed a significant increase in colonized tumor cells in the lung compared with that in wild-type sEV-treated mice (P < 0.001)." (PMID 34646366, 2021). "The qRT-PCR results also showed that the mRNA expressions of COL I, COL III, LOX, and LOXL2 in tumor tissues were higher than those in normal tissues." (PMID 34335820, 2021). "Our results support the conclusion of Cui's work 53, 54, because tumor cell-secreted LOXL2 protein includes soluble form and those encapsulated in extracellular vesicles." (PMID 34646366, 2021).
tumor (continued). "Genes whose upregulation is associated with some cancers (TMEM140, ANXA10, ZNF69, CA9, LOXL2, PAGE3, ELFN1) were also on this list, as was a putative tumor suppressor (DEC1)." (PMID 33601339, 2021). "Lysyl oxidase-like 2 (LOXL2) is an extracellular matrix-remodelling enzyme that catalyses the cross-linking of collagen and elastin components and is expressed in desmoplastic tumours." (PMID 33917882, 2021). "Here, we described that LOXL2, induced by hypoxia, couples the Warburg effect to tumor progression in PDAC." (PMID 34836938, 2021). "It would be useful in the future to measure this behavior directly by monitoring both LOXL2 concentration and compliance maps for an in vitro tumor spheroid." (PMID 33807227, 2021). "Here, we show that LOXL2 delivered by tumor cell-derived sEVs to fibroblasts induced PMN formation of HNSCC." (PMID 34646366, 2021). "Together, these data indicate that HIF1α is indispensable for LOXL2-mediated tumor-promoting functions in PDAC cells." (PMID 34836938, 2021). "It is noteworthy that in vitro experiments with LOXs inhibitors showed a prominent role of LOXL-2 versus LOX in tumor growth, collagen cross-linking, angiogenesis, and fibroblast activation." (PMID 31650200, 2020). "FACS analysis of tumor tissues at the treatment endpoints showed that the combination of PD-L1 and LOXL2 inhibition significantly increased total CD8+ TILs and decreased exhausted CD8+ T cell subpopulations." (PMID 32908154, 2020). "Knockdown of LOXL2 in CCA cells blunted tumor growth and microvessel density in a xenograft nude mouse model." (PMID 33371259, 2020). "Tumor-secreted LOXL-2 has been described to activate stroma fibroblasts (to α-SMA + myofibroblasts) and vascular smooth muscle cells through the H2O2-mediated activation of FAK/SRC and ErbB2/Erk2 signaling." (PMID 31650200, 2020). "In turn, LOXL2 induced aberrant activation of EMT crosslinked collagen in ECM remodeling for tumor microenvironment." (PMID 32211324, 2020). "Reduction in tumor collagen deposition through LOXL2 suppression increases T cell infiltration, diminishes exhausted T cells, and abrogates resistance to anti-PD-L1." (PMID 32908154, 2020). "Overexpressed mRNA of LOX and LOXL2 were significantly correlated with tumor grade, individual cancer stages and nodal metastasis status in KIRC from TCGA samples." (PMID 32970930, 2020). "Tumor suppressor miRNAs, miR-26, and miR-29, by targeting LOXL2, suppress tumor metastasis and the recruitment of myeloid cells to the metastatic site." (PMID 33321819, 2020). "The interaction of LOXL2 with α5β1 integrin warrants further investigation in the context of angiogenesis and cancer because α5β1 integrin is expressed by neovessels and tumor cells." (PMID 33383846, 2020). "LOX and LOXL2 were significantly over‐expressed in KIRC tumor compared to normal tissue using GEPIA." (PMID 32970930, 2020). "Consistently, ellagic acid inhibition of LOXL2 in combination with anti-PD-L1 significantly reduced tumor volume and weight." (PMID 32908154, 2020). "Although reducing intratumoral collagen sensitized lung tumors to PD-L1 blockade even at later stages of tumor formation, LOXL2 inhibition was required immediately following tumor implantation to prevent baseline collagen deposition." (PMID 32908154, 2020). "Two tumor suppressor miRNAs, miR-26 and miR-29 target lysyl oxidase-like 2 (LOXL-2), which is a collagen-modifying enzyme, crucial for tissue remodeling and metastasis." (PMID 33321819, 2020). "Further analysis demonstrated that higher mRNA expression of LOX and LOXL2 were significantly correlated with poor survival, tumor grade, individual cancer stages, and nodal metastasis status." (PMID 32970930, 2020). "Tumor cell expression of lysyl oxidase-like 2 (LOXL2) has been shown to regulate the EMT transcription factor Snail1 and can additionally interact with the bHLH transcription factor E47 to downregulate E-cadherin and induce EMT." (PMID 32391382, 2020).